CASP6 (caspase 6)
Diseases named in the same sentence as CASP6 in open-access papers (continued):
Sharing a sentence is not in itself a finding about the gene and the disease.
cardiac arrest (2 papers, 2019 to 2024). Cessation of breathing and/or cardiac function. "We set out to develop an assay detecting the neo-epitope generated by caspase-6 cleavage of GFAP (GFAP-C6), and to assess the ability of GFAP-C6 to reflect pathological processes in patients suffering a cardiac arrest and subsequent global cerebral ischemia." (PMID 31693684, 2019). "A previous study determined the neoepitope that is generated by caspase-6-mediated cleavage of GFAP (GFAP-C6) and assessed the ability of GFAP-C6 to reflect pathological processes in patients suffering from cardiac arrest (CA) and subsequent global cerebral ischemia." (PMID 39001884, 2024).
colitis (2 papers, 2014 to 2024). Inflammation of the colon. "In conclusion, Casp6 is strongly expressed and activated in tumors formed in a mouse model of colitis-associated tumorigenesis." (PMID 25470254, 2014).
COVID-19 (2 papers, 2022). A disease caused by infection with severe acute respiratory syndrome coronavirus 2. "Consistent with the apoptosis trend of Tim-3+ NKT cells, an elevated expression level of almost all caspase genes in Tim-3+ NKT cells was observed in controls and patients with mild and severe COVID-19, especially caspase-2, caspase-3, caspase-6, and caspase-9." (PMID 35250975, 2022).
influenza (2 papers, 2021). An acute viral infection of the respiratory tract, occurring in isolated cases, in epidemics, or in pandemics; it is caused by serologically different strains of viruses (influenzaviruses) designated A, B, and C, has a 3-day incubation period, and usually lasts for 3 to 10 days. "Further studies of histone induced inflammation or NET induced inflammation in vivo could evaluate the role of caspase 6, since histones and NETs are implicated in pathophysiology of influenza." (PMID 32803840, 2021). "Caspase‐6 was involved in pyroptosis in host defense against influenza A virus (IAV) infection." (PMID 34459122, 2021).
intestinal cancer (2 papers, 2016 to 2025). "We detected that Lamin A, which functions downstream of caspase 6, was significantly upregulated in the BF-rTK/GCV treatment group in intestinal cancer." (PMID 27275821, 2016). "Thus, our data demonstrate that Caspase‐6, but not Caspase‐8, activates GSDMC in intestinal cancer." (PMID 40213993, 2025).
lung carcinoma (2 papers, 2021 to 2023). "The present study revealed that the SMAC mimetic compound AT101 treatment down-regulated XIAP, cIAP1, and cIAP2 mRNA and protein expressions while increasing caspase-6 and caspase-7 mRNA and protein expression levels in NCI-H522 lung cancer cell line to favor total apoptosis in these cells." (PMID 34712428, 2021). "This study proved for the first time that the exosomes secreted by lung cancer cell line H1299 could significantly change the expression of apoptosis related proteins MAP2K1, TUBA1C, RELA, and CASP6, thus promoting apoptosis of human astrocyte line SVG P12 cells." (PMID 36859173, 2023).
neuropathic pain (2 papers, 2017). Chronic pain caused by damage to nerve fibers. "Indeed, knock out of CASP6 attenuated mechanical allodynia in the paclitaxel model of chemotherapy induced neuropathic pain (CIPN)." (PMID 28839165, 2017). "There is increasing evidence that CASP1, CASP6, and CASP11 activation is involved in microglia activation and the maturation of proinflammatory cytokines in inflammatory and neuropathic pain conditions." (PMID 28270702, 2017).
osteoarthritis (2 papers, 2022 to 2024). A noninflammatory degenerative joint disease occurring chiefly in older persons, characterized by degeneration of the articular cartilage, hypertrophy of bone at the margins and changes in the synovial membrane. "The genes enriched in the osteoarthritis pathway revealed by IPA of the DEGs in the palovarotene-treated chondrocytes included various matrix catabolic genes (Adamts4, Adamts5, Mmp9, Mmp10, Mmp12, and Mmp13) and cell death-related genes (Casp1, Casp3, and Casp6)." (PMID 39062860, 2024).
osteosarcoma (2 papers, 2022 to 2024). A usually aggressive malignant bone-forming mesenchymal neoplasm, predominantly affecting adolescents and young adults. "Meanwhile, research has confirmed the role of CASP6, a gene highly expressed in subtype B, in reducing the risk of osteosarcoma patient prognosis." (PMID 39015570, 2024). "Through the survival analysis of the single gene, the BAK1, CASP6, and GSDMA were found to be linked to the prognosis of osteosarcoma." (PMID 36244998, 2022). "By the Lasso Cox regression analysis, 6 key PRGs were screened for constructing the optimal model, namely CHMP4C, GZMA, BAK1, CASP1, CASP6, and GSDMA, and a six PRGs signature was successfully constructed for osteosarcoma." (PMID 36244998, 2022).
Sepsis (2 papers, 2017 to 2023). Sepsis is defined as life-threatening organ dysfunction caused by a dysregulated host response to infection. "In addition, the authors of this study demonstrated that caspase-6-/- mice were protected to some degree during cecal lesion induced peritonitis and sepsis." (PMID 28686630, 2017).
age (1 paper, 2017). A temporal measurement of the time period elapsed since an identifiable point in the life cycle of an organism. "Human Casp6 overexpression in the CA1 region of the hippocampus results in age-dependent episodic memory impairments measured by NOR." (PMID 28241839, 2017).
amebiasis (1 paper, 2017). A parasitic infectious disorder caused by amoebas. "Therefore, further studies in the role of caspase-6 in gut inflammatory responses are warranted to assess whether this mechanism is unique to amebiasis or whether caspase-6 plays a broader role in triggering cytokine secretion and cytoskeletal remodeling." (PMID 28837696, 2017).
amyloid (1 paper, 2012). "Additionally, caspase-6 also contributes to the processing of amyloid precursor protein and the deposition of Alzheimer's disease-related amyloid in the brain." (PMID 22606319, 2012).
argyrophilic grain disease (1 paper, 2025). A tauopathy characterized pathologically by the presence of silver stain positive lesions called argyrophilic grains, oligodendrocytic coiled bodies, and neuronal tau-positive pretangles. "The presence of active caspase-6 and truncated tau forms (Δtau-13 and -402) is significant in AD and, to a lesser extent, in PiD but not in argyrophilic grain disease (AGD), CBD, or PSP." (PMID 38733347, 2025).
Ataxia (1 paper, 2022). Ataxia refers to impaired coordination of voluntary muscle movement. "Among the genes related to cerebellar volume in the four substructure GWASs we find genes related to ataxia (PEX7, MRPS27, PTK2), neurodevelopment (YPEL3, CASP6, TRIM11, GNB5) and microcephaly (PDCD6IP, USP28)." (PMID 35546225, 2022).
brain infarction (1 paper, 2015). Tissue necrosis in any area of the brain, including the cerebral hemispheres, the cerebellum, and the brain stem. "As CASP6 or CASP8 inhibition were neuroprotective following retinal ischemia, we tested the effect of these interventions on brain infarction in a thromboembolic model of MCAO." (PMID 26539914, 2015).
cerebral malaria (1 paper, 2019). A sequestration of Plasmodium falciparum in the brain, which can cause coma and/or seizures. "Consequently, we propose that malarial hemozoin promotes oxidative stress- and caspase-6-mediated neuronal loss, which explains the presence of neurological sequelae in cerebral malaria." (PMID 31332667, 2019).
colonic adenocarcinomas (1 paper, 2013). "Both in normal colonic mucosa and in some colonic adenocarcinomas, mucinous cells (goblet cells) often contain one or several cytoplasmic granules, which are immunoreactive for active Casp6." (PMID 24265764, 2013).
colorectal adenocarcinoma (1 paper, 2024). The most common type of colorectal carcinoma. "In colorectal adenocarcinoma cells, phosphorylation of the Ser254 of caspase-6 by AMPK related protein kinase 5 has been identified." (PMID 39497227, 2024).
colorectal tumor (1 paper, 2025). "Taken together, our data indicate that Caspase‐6 activates intestinal epithelial GSDMC to promote colorectal tumor progression." (PMID 40213993, 2025). "Here, we found that Hypoxia and low‐glucose conditions lead to colorectal tumor cell pyroptosis through Caspase‐1/Caspase‐6/GSDMC2/3/4 axis in mouse model." (PMID 40213993, 2025). "Hypoxic and low‐glucose conditions in tumor tissues trigger colorectal tumor cell pyroptosis via sequential activation of the Caspase‐1/Caspase‐6/GSDMC axis." (PMID 40213993, 2025).
corneal infection (1 paper, 2022). A viral or bacterial infectious process affecting the cornea. "We next used a mouse corneal infection model to examine the role of caspase-6 in HSV-1 corneal infection." (PMID 36146839, 2022). "We then used a corneal infection model with WT and Casp6–/– mice." (PMID 36146839, 2022). "Thus, we concluded that caspase-6 does not contribute to the defense against HSV-1 corneal infection." (PMID 36146839, 2022).
dengue (1 paper, 2025). "We found that, MMP-2 concentrations have significantly upregulated the expression profile of apoptotic genes, that is, caspase-3, Bad, Bax, caspase-6, and DAPK-1 in lung epithelial cells suggesting its apoptosis causing property in dengue pathogenesis." (PMID 41459161, 2025).
diabetes (1 paper, 2021). "For example, in the amelioration of diabetes, miR-129-3p decreases the apoptosis and recruitment of neutrophils by regulating the translation of Casp6 and Ccr2, whereas miR-129-5p inhibits ECM degradation by inhibiting the expression of Sp1-mediated MMP9." (PMID 34777000, 2021).
E. coli infection (1 paper, 2021). "In line with the previous findings that apoptotic caspases suppress type I IFN production, we observed that the loss of CASP6 increased the expression of Ifnb in response to E. coli infection." (PMID 34740613, 2021). "Loss of CASP6 resulted in reduced CASP1 activation following E. coli infection." (PMID 34740613, 2021). "In response to E. coli infection, neither Nlrp3 nor Il1b mRNA levels were decreased in Casp6−/− BMDMs compared with those in WT BMDMs." (PMID 34740613, 2021).
fucosidosis (1 paper, 2023). "A detailed examination of OL status in a canine model of fucosidosis identified significant OL loss in the corpus callosum and cerebellar white matter, which stabilized by 16 weeks of age, as visualized by decreased CNP, MAG, MAL and PLP1 expression, and reduced CNP and increased CASP6 staining." (PMID 37183607, 2023).
gastric tumors (1 paper, 2023). "Our results confirmed that the expression of GPX4, CASP6, IL-6, CASP5, CASP4, and TIRAP was greatly up-regulated in gastric tumors relative to normal tissues." (PMID 37595258, 2023).
gram-negative bacterial infections (1 paper, 2021). Infections caused by bacteria that show up as pink (negative) when treated by the gram-staining method. "To determine the effect of the catalytic activity of CASP6 during gram-negative bacterial infection, we established a mouse model carrying a mutation in CASP6 that created a catalytically dead version of the protein, Casp6C146A/C146A (Casp6CA/CA)." (PMID 34740613, 2021). "In this study, we discovered that CASP6 contributes to gram-negative bacterial infection-induced CASP11-NLRP3 inflammasome activation." (PMID 34740613, 2021). "Together, these results suggest that CASP6 is required for optimal CASP11-NLRP3 inflammasome activation following gram-negative bacterial infections." (PMID 34740613, 2021). "In this study, we found that during gram-negative bacterial infections, CASP6 plays a critical role in promoting CASP11-NLRP3 inflammasome activation." (PMID 34740613, 2021). "Because we observed that CASP6 contributed to the activation of CASP11 during gram-negative bacterial infection, we hypothesized that the catalytic activity of CASP6 would be important in regulating the CASP11-NLRP3 inflammasome." (PMID 34740613, 2021). "We found that the formation of the p26 cleavage fragment of CASP11 was reduced in Casp6−/− BMDMs infected with either E. coli or C. rodentium for 10 and 20 h, suggesting that CASP6 is involved in the processing of CASP11 for its activation during gram-negative bacterial infection." (PMID 34740613, 2021). "To investigate whether CASP6 also has a role in the regulation of the CASP11-NLRP3 inflammasome during gram-negative bacterial infections, we infected bone marrow-derived macrophages (BMDMs) isolated from WT and Casp6−/− mice with the enteric bacteria Escherichia coli or Citrobacter rodentium." (PMID 34740613, 2021). "Together, our results suggest that CASP6 contributes to CASP11 activation, thereby regulating the activation of pyroptosis during gram-negative bacterial infection." (PMID 34740613, 2021). "Overall, our data suggest that CASP6 does not regulate the expression of the components of the CASP11-NLRP3 inflammasome during gram-negative bacterial infection." (PMID 34740613, 2021). "We observed comparable activation of ERK and NF-κB in WT and Casp6−/− BMDMs upon infection with E. coli or C. rodentium, suggesting that CASP6 is dispensable for the priming step of gram-negative bacterial infection-induced CASP11-NLRP3 inflammasome activation." (PMID 34740613, 2021). "However, the role of CASP6 in response to gram-negative bacterial infection has not been investigated." (PMID 34740613, 2021). "Using in vitro cellular systems with bone marrow-derived macrophages and 293T cells, we found that CASP6 can directly process CASP11 by cleaving at Asp59 and Asp285, the CASP11 auto-cleavage sites, which could contribute to the activation of CASP11 during gram-negative bacterial infection." (PMID 34740613, 2021).
heart failure (1 paper, 2024). Inability of the heart to pump blood at an adequate rate to meet tissue metabolic requirements. "In a heart-failure mouse model, desmin was cleaved by caspase-6, losing its mechanical and nonmechanical properties and forming cytoplasmic aggregates." (PMID 39195218, 2024).
intestinal tumors (1 paper, 2025). "Mechanistically, we revealed that GSDMC was activated by Caspase‐6 in intestinal tumors under hypoxia and low‐glucose condition." (PMID 40213993, 2025).
ischemia (1 paper, 2015). A hypoperfusion of the BLOOD through an organ or tissue caused by a PATHOLOGIC CONSTRICTION or obstruction of its BLOOD VESSELS, or an absence of BLOOD CIRCULATION. "In this study, we evaluated whether caspase-6 or -8 inhibitors can reduce cerebral or retinal injury after ischemia." (PMID 26539914, 2015). "Our data implicate CASP6 as an important mediator of ischemia-induced neuronal degeneration." (PMID 26539914, 2015). "After showing that CASP6 or CASP8 inhibition ameliorated the neuropathological consequences of ischemia, we evaluated whether these interventions affect caspase activation in the brain and retina." (PMID 26539914, 2015). "To evaluate the possible neuroprotective effects of CASP6 or CASP8 knockdown, we injected siRNAs into the vitreous chamber of the eye after ischemia." (PMID 26539914, 2015). "Together, these results reveal that CASP6 and CASP8 have an important role in the degeneration of retinal ganglion cells after ischemia." (PMID 26539914, 2015).
keloid (1 paper, 2021). An irregularly shaped, elevated mark on the skin caused by deposits of excessive amounts of collagen during wound healing. "Another microarray study revealed that keloid-prone patients exhibited alteration of caspase 6 and 14 transcripts." (PMID 34384362, 2021).
liver fibrosis (1 paper, 2023). "Treatment with AMPK activator and caspase-6 inhibitor for two weeks significantly reduced the death of hepatocytes and liver fibrosis." (PMID 38202710, 2023). "Once the activation of AMPK is reduced, pro-apoptotic caspase-6 cleavage induces the release of cytochrome c, which consequently supports the activation of the executioner caspases and apoptosis in a feed-forward mechanism, leading to liver injury and liver fibrosis." (PMID 38202710, 2023).
liver inflammation (1 paper, 2023). "Activation of macrophage NR4A1 or SOX9 in Caspase 6-deficient livers aggravated liver inflammation." (PMID 36977670, 2023).
male infertility (1 paper, 2024). The inability of the male to effect fertilization of an ovum after a specified period of unprotected intercourse. "Moreover, we demonstrated that decreased AMPK activity and increased caspase-6 activity in the testis from AdipoR1 KO mice and that AdipoR1 KO mice were associated with male infertility due to smaller testis, lower sperm counts and lower sperm motility." (PMID 38459078, 2024). "This was the first study to demonstrate that decreased AdipoR1/AMPK signaling led to increased caspase-6 activity/increased apoptosis in the testis thus likely accounting for male infertility." (PMID 38459078, 2024). "Our study showed that decreased adiponectin/AdipoR1 signaling accounts for male infertility as it involves apoptosis via the AMPK-caspase-6 axis." (PMID 38459078, 2024).
memory impairment (1 paper, 2023). "Caspase-6 is also considered an early marker of AD that might contribute to neurodegeneration and memory deficit as shown in a transgenic mouse model overexpressing caspase-6 with memory impairment." (PMID 36806186, 2023).
metastatic tumors (1 paper, 2024). "-The increased expression of activated caspase-6 in the skin compartment of primary and metastatic tumors corresponds to decreased levels of AP-2α and c-kit, while the expression of activated caspase-3 characterizes metastatic cells." (PMID 39329914, 2024).
middle cerebral artery infarction (1 paper, 2023). Necrosis occurring in the middle cerebral artery distribution system which brings blood to the entire lateral aspects of each cerebral hemisphere. "Moreover, CASP3, CASP6, as well as GOT1 and IL1RN, have been implicated in vascular dementia, middle cerebral artery infarction and transient cerebral ischemia (FDR = 0.041)." (PMID 38107644, 2023).
Nephropathy (1 paper, 2013). A nonspecific term referring to disease or damage of the kidneys. "We also examined the activation of the apoptotic marker caspase 6, which was shown to be involved in PTEC apoptosis during nephropathy." (PMID 24400007, 2013).
pancreas cancer (1 paper, 2010). "Most of the genes in the verification data are functionally cancer related including the genes showing sex difference Both genes CASP6 and HOXA9 are hypermethylated, leading to decreased gene expression in pancreas cancer tissue." (PMID 20386599, 2010).
pheochromocytoma (1 paper, 2020). "Knockdown of lncRNA BC088414 decreased the mRNA expression of caspase-6 (Casp6) and β2-adrenoceptor (Adrb2), which are apoptosis-related genes, thereby reducing the cell apoptosis and promoting cell proliferation in pheochromocytoma-12 (PC-12) neural cells." (PMID 33321920, 2020).
progressive neurodegenerative disorder (1 paper, 2023). "In research for HD, as well as a progressive neurodegenerative disorder, the researchers described that ZNF148 directly interacted with three known-HD genes (BCL2, CASP6, and IRS2)." (PMID 37360784, 2023).
schizophrenia (1 paper, 2015). A major psychotic disorder characterized by abnormalities in the perception or expression of reality. "In order to confirm the specificity of sox11 mediated reduction in caspase-6 activity, we co-transfected caspase-6 with two other proteins, FEZ1 which was identified from the yeast-two hybrid screen and DISC1 which is a known susceptibility protein for Schizophrenia." (PMID 26505998, 2015).
silicosis (1 paper, 2022). Silicosis is a respiratory disease caused by breathing in (inhaling) silica dust. "Since activation of Caspase-6 is induced by the upstream Caspase-3 in the apoptotic pathway, the Caspase-6 activity we observed in the silicosis models may be a redundant protein function." (PMID 36459518, 2022). "The activation of Caspase-3 and Caspase-6 is not dependent on Nlrp3, suggesting there are other singalings to activate silicosis induced cell death beside Nlrp3." (PMID 36459518, 2022).